USP39 (ubiquitin specific peptidase 39)
Diseases named in the same sentence as USP39 in open-access papers (continued):
Sharing a sentence is not in itself a finding about the gene and the disease.
endometrial cancer (5 papers, 2024 to 2025). Primary or metastatic malignant neoplasm involving the endometrium (mucous membrane that lines the endometrial cavity). "Research on endometrial cancer reveals that H3K18la modification in the promoter region of ubiquitin specific peptidase 39 (USP39) upregulates its expression." (PMID 40589733, 2025). "In endometrial cancer cells, histone lactonization can stimulate USP39 overexpression by enriching H3K18la in the USP39 promoter region, thereby promoting the growth and proliferation of endometrial cancer cells." (PMID 40672756, 2025). "To verify the effect of histone lactylation and USP39 on endometrial cancer, we established an EC xenograft tumor model in nude mice and evaluated the outcomes in vivo." (PMID 38459014, 2024). "In addition, histone lactylation promotes malignant progression by promoting the expression of ubiquitin specific peptidase 39 (USP39) targeting the PI3K/AKT/HIF-1α signaling pathway in endometrial cancer." (PMID 40255565, 2025).
esophageal squamous cell carcinoma (5 papers, 2021 to 2025). Esophageal squamous cell carcinoma (ESCC) is a type of esophageal carcinoma (EC) that can affect any part of the esophagus, but is usually located in the upper or middle third. "Here we report that USP39 is differentially upregulated in human esophageal squamous cell carcinoma (ESCC) and its expression is significantly associated with clinicopathological characteristics including differentiation status and TNM stage." (PMID 34123832, 2021). "USP39 is upregulated in esophageal squamous cell carcinoma (ESCC) tissues, with high expression negatively associated with patient prognosis." (PMID 40672756, 2025). "USP39's association with the augmented migratory and invasive capacities of esophageal squamous cell carcinoma (ESCC) cells fosters tumor progression and metastasis." (PMID 38702734, 2024). "USP39 expression is up-regulated in cancers such as human esophageal squamous cell carcinoma (ESCC)." (PMID 38270460, 2024).
liver cancer (5 papers, 2021 to 2023). An epithelial or non-epithelial malignant neoplasm that arises from the liver. "Using a conditional Usp39 overexpression mouse model, we demonstrated that USP39 was a driver of liver cancer as well as a potent regulator of AS." (PMID 37821439, 2023). "The Kaplan–Meier analysis found that the high expression of USP39 in liver cancer was closely related to the poor prognosis of patients." (PMID 35875077, 2022). "Subsequently, USP39 was found to stabilize the SP1 expression to induce malignant biological behaviors of liver cancer." (PMID 36582601, 2022). "Meanwhile, the level of USP39 protein in liver cancers was increased compared with that in normal liver tissue from the HPA." (PMID 34987596, 2021). "In this study, results from multiple databases showed that USP39 was differentially expressed in liver cancer tissues compared with normal tissues." (PMID 34987596, 2021). "In human liver cancer cells, USP39 promoted tumor proliferation in a spliceosome-dependent manner." (PMID 37821439, 2023). "New research shows that USP39 plays a key role in the occurrence and development of liver cancer." (PMID 35875077, 2022). "USP39 may promote the malignancy of liver cancer by participating in the regulation of the epithelial–mesenchymal transition (EMT) pathway of HCC." (PMID 35875077, 2022). "Several studies demonstrated the tumor-promoting role of USP39 in liver cancer." (PMID 36582601, 2022). "Therefore, USP39 can target Sp1 to promote liver cancer cell proliferation." (PMID 35875077, 2022). "Interestingly, a study in liver cancer model showed that tumor cells that failed at H3K9Ac/H3K9Me3 transition, could lead to the hyperacetylation of H3K9 and increased expression of many oncogenes such as Kras, Ercc1, Cdk6, Usp39, and Mapre352." (PMID 36064736, 2022).
pancreatic cancer (5 papers, 2019 to 2025). "USP39 has been found to be aberrantly expressed in pancreatic cancer tissues and cells, and regulates tumorigenesis and development by participating in a variety of biological processes." (PMID 40672756, 2025). "miR-133a directly targets USP39 and promotes pancreatic cancer progression through the AKT signaling pathway." (PMID 40990019, 2025). "Interestingly, in pancreatic cancer, miR-133a has also been reported to directly target USP39, thereby promoting pancreatic cancer progression through the activation of the AKT signaling pathway." (PMID 40990019, 2025). "In pancreatic cancer, USP39 was correlated with TNM stage, depth of invasion, and poor survival." (PMID 34987596, 2021). "In addition, as a target of microRNA-133a, USP39 promotes progression of pancreatic cancer via the AKT pathway." (PMID 30898977, 2019).
renal cell carcinoma (5 papers, 2021 to 2025). "USP39 exhibits elevated expression in renal cell carcinoma tumor tissues and cells compared to normal kidney tissues, and patients with higher USP39 levels experience significantly reduced overall survival (OS)." (PMID 40672756, 2025). "USP39 can affect the development of renal cell carcinoma by activating multiple signaling pathways and indirectly regulating the variable splicing of VEGF-A pre-mRNA." (PMID 40672756, 2025).
gastric cancer (4 papers, 2024 to 2025). A primary or metastatic malignant neoplasm involving the stomach. "Hence, in our following experiments, we explored the influence of USP39 on gastric cancer cells and elucidated the underlying molecular mechanism." (PMID 39260689, 2024). "USP39’s role in gastric cancer, which involves regulating tumor progression through interactions with PARP, RBM39, and miR-133a, emphasizes its potential as a promising clinical target for therapeutic applications." (PMID 40672756, 2025). "The upregulation of miR-133a expression and/or the downregulation of USP39 inhibited the proliferation of gastric cancer cells." (PMID 40990019, 2025). "To explore the function of USP39 on the regulation of gastric cancer cells, we first assessed its mRNA expression in tumor tissues." (PMID 39260689, 2024). "Our work also demonstrated that USP39 accelerated the growth and metastasis of gastric cancer cells partially through RBM39." (PMID 39260689, 2024). "We further investigate the influence of USP39 on the growth and metastasis of gastric cancer cells and reveal the molecular mechanism by which USP39 executes its biological function and its association with RBM39 expression." (PMID 39260689, 2024). "Taken together, this work and previous data revealed that both USP39 and RBM39 promoted the growth of gastric cancer cells and their high expression was associated with poor patient survival." (PMID 39260689, 2024). "Our previous work discovered that RBM39 promoted the growth of gastric cancer cells and this work revealed that USP39 upregulated RBM39." (PMID 39260689, 2024). "USP39 overexpression promotes while its knockdown attenuates the growth, colony formation, migration, and invasion of gastric cancer cells." (PMID 39260689, 2024). "Bioinformatic analysis discloses that USP39 is increased in gastric cancer tissues and its elevation shortens the duration of overall survival for gastric cancer patients." (PMID 39260689, 2024). "We also elucidated the molecular mechanism by which USP39 promotes the growth and metastasis of gastric cancer cells partially by regulating RBM39." (PMID 39260689, 2024). "Third, Kaplan–Meier survival analysis revealed that high USP39 mRNA expression results in poor survival of gastric cancer patients." (PMID 39260689, 2024). "Next, we sought to ask how USP39 elevates the RBM39 protein level in gastric cancer cells through the following experiments." (PMID 39260689, 2024). "miR-133a has previously been shown to target USP39 in gastric cancer, suggesting that there may be specific binding between USP39 and miR-133a in a variety of malignant tumors." (PMID 40672756, 2025). "First, we tested the effect of USP39 on RBM39 in AGS gastric cancer cells." (PMID 39260689, 2024). "Indeed, it has been revealed that the genetic depletion of USP39 suppressed the proliferation and growth of gastric cancer cells." (PMID 39260689, 2024). "Analysis of The Cancer Genome Atlas database revealed that USP39 mRNA was highly expressed in the primary gastric tumor and was significantly elevated at the different stages of gastric cancer tissues although the relative level at various stages remained similar." (PMID 39260689, 2024). "Interestingly, overexpression of RBM39 partially restores the impact of USP39 depletion, while RBM39 knockdown partially abolishes the effect of USP39 overexpression on the growth, colony formation, migration, and invasion of gastric cancer cells." (PMID 39260689, 2024). "Expression of USP39 significantly elevated RBM39 while USP39 knockdown attenuated RBM39, which was also observed in HGC27 gastric cancer cells." (PMID 39260689, 2024). "Therefore, we asked whether USP39 modulates these functions in gastric cancer cells through RBM39." (PMID 39260689, 2024). "To further confirm the potential correlation between USP39 and RBM39, we immunoblotted these two proteins in different gastric cancer cell lines and in paratumor and tumor tissues from gastric cancer patients." (PMID 39260689, 2024).
gastric cancer (continued). "Therefore, we would like to test whether USP39 also impacts the growth of gastric cancer cells." (PMID 39260689, 2024). "After we demonstrated the interaction between USP39 and RBM39, we sought to test whether and how USP39 regulates RBM39 in gastric cancer cells." (PMID 39260689, 2024). "Third, to test whether this interaction occurs endogenously in gastric cancer cells, we immunoprecipitated endogenous USP39 from MKN45 and HGC27 cell lysates using an anti-USP39 antibody and protein A/G agarose and detected the presence of endogenous RBM39 in the immunoprecipitates." (PMID 39260689, 2024). "Although it has been shown that USP39 has played significant roles in regulating the ubiquitination and stability of multiple proteins, it is unclear whether it impacts RBM39 and regulates its biological functions in gastric cancer cells." (PMID 39260689, 2024).
leukemia (4 papers, 2019 to 2025). A malignant (clonal) hematologic disorder, involving hematopoietic stem cells and characterized by the presence of primitive or atypical myeloid or lymphoid cells in the bone marrow and the blood. "A previous study showed that high expression of USP39 was associated with poor survival of patients with leukemia." (PMID 34987596, 2021). "USP39 was highly expressed in leukemia cells, and evidence from the TCGA database indicated that its overexpression is linked to poor prognosis." (PMID 40672756, 2025). "Flow cytometry analysis showed that the cell cycle was arrested in the G2/M phase, and apoptosis was promoted, indicating that USP39 contributes to the growth and proliferation of leukemia cells." (PMID 40672756, 2025). "Taken together, our findings implicate that USP39 promotes the development of human leukemia by regulating cell cycle, survival, and proliferation of the cells." (PMID 30898977, 2019). "However, the roles of USP39 in human leukemia and the underlying mechanism remain unknown." (PMID 30898977, 2019). "Molecular, cellular and bioinformatic analysis demonstrated that USP39 regulated the growth, cell cycle, and survival of leukemia cells." (PMID 30898977, 2019). "We observed that lentivirus-mediated knockdown of USP39 significantly repressed the proliferation rate of leukemia cells." (PMID 30898977, 2019). "Our qRT-PCR and Western blot results showed that USP39 expression was significantly knocked down in leukemia cell lines HL-60 and Jurkat cells." (PMID 30898977, 2019). "Taken together, these findings demonstrated that USP39 was overexpressed in human leukemia cells and high expression of USP39 predicted poor survival." (PMID 30898977, 2019). "We showed that USP39 knockdown induced the cell cycle arrest at G2/M phase in two lines of leukemia cells." (PMID 30898977, 2019). "Since the high expression of USP39 in human leukemia, we next aimed to investigate the roles of USP39 in regulating the cellular behavior of leukemia cells." (PMID 30898977, 2019). "Taken together, these findings demonstrated that USP39 knockdown inhibited the growth of leukemia cells in vitro." (PMID 30898977, 2019). "Bioinformatic analysis revealed that USP39 significantly modified the transcriptional profile of leukemia cells." (PMID 30898977, 2019). "Our loss-of-function experiments demonstrated that knockdown of the expression of USP39 repressed the proliferation of leukemia cells, induced cell cycle arrest, and cell apoptosis." (PMID 30898977, 2019). "To explore the potential roles of USP39 in human leukemia, we first examined the expression of USP39 in human leukemia cells." (PMID 30898977, 2019). "We observed that USP39 was overexpressed in human leukemia, which was correlated with the survival of patients." (PMID 30898977, 2019). "The results showed that high expression of USP39 in leukemia cells was correlated with poor survival of the patients." (PMID 30898977, 2019). "We observed that the expression of USP39 was up-regulated in human leukemia cells and the high expression of USP39 was correlated with poor survival of the patients with leukemia." (PMID 30898977, 2019). "The IPA pathway analysis showed that USP39 regulated diverse pathways that were involved in cancer, including Rac signaling, leukemia extravasation signaling, tissue factor in cancer, focal adhesion kinase (FAK) signaling." (PMID 30898977, 2019). "Lentivirus-mediated knockdown of USP39 repressed the proliferation and colony formation of human leukemia cell lines HL-60 and Jurkat cells." (PMID 30898977, 2019). "Mechanism study showed that USP39 knockdown induced the arrest of cell cycle and apoptosis of leukemia cells." (PMID 30898977, 2019). "We observed that the expression of USP39 was significantly up-regulated in human leukemia and high expression of USP39 in human leukemia cells predicted poor overall survival." (PMID 30898977, 2019).
leukemia (continued). "The expression of USP39 mRNA level was significantly up-regulated in the leukemia cells compared with those from the controls." (PMID 30898977, 2019). "USP39 controls the proliferation, cell cycle, and apoptosis of leukemia cells." (PMID 30898977, 2019). "In addition, the knockdown of USP39 also reduced the number and size of clones formed by leukemia cells, implicating that the colony formation of leukemia cells was controlled by USP39." (PMID 30898977, 2019). "Furthermore, we performed a microarray assay and found that USP39 regulated the expression of diverse genes in human leukemia cells, including IRF1, Caspase 8, and SP1, which were validated by qRT-PCR experiments." (PMID 30898977, 2019). "We also tested the expression content of USP39 in three leukemia cell lines (HL-60, Jurkat, K562)." (PMID 30898977, 2019). "In conclusion, we identify USP39 as an oncogene-like protein in human leukemia." (PMID 30898977, 2019). "In the present study, we identified the roles of USP39 in human leukemia." (PMID 30898977, 2019). "Since the high expression of USP39 in human leukemia, we next investigated whether USP39 expression level was correlated with survival using the TGCA database." (PMID 30898977, 2019). "In the present work, we identify USP39 as a regulator of human leukemia." (PMID 30898977, 2019). "USP39 also controls the cell cycle and apoptosis of leukemia cells." (PMID 30898977, 2019). "We next investigated the effects of USP39 on the colony formation capacity of leukemia cells." (PMID 30898977, 2019). "The relative Ct value indicated that USP39 was expressed at high level in leukemia cell lines." (PMID 30898977, 2019). "Knockdown or IRF1 partially restored the proliferation rate of leukemia cells with USP39 knockdown." (PMID 30898977, 2019). "The results also showed that the expression of USP39 was increased in leukemia samples." (PMID 30898977, 2019). "Collectively, these findings demonstrated that USP39 regulates cell cycle of leukemia cells." (PMID 30898977, 2019). "Here in the present work, we aimed to elucidate the function of USP39 in human leukemia." (PMID 30898977, 2019). "We also investigated the effects of USP39 knockdown on the apoptosis of leukemia cells." (PMID 30898977, 2019). "We next explored whether cell cycle arrest contributed to the effects of USP39 on the growth of leukemia cells." (PMID 30898977, 2019). "Therefore, USP39 also controls the survival of leukemia cells." (PMID 30898977, 2019). "The functions of the USP39 in human leukemia remains unknown." (PMID 30898977, 2019). "In addition, USP39 knockdown significantly induced apoptosis of leukemia cells." (PMID 30898977, 2019). "Therefore, USP39 may serve as a potential target for the treatment of human leukemia." (PMID 30898977, 2019). "However, the roles of USP39 in human leukemia remain unknown." (PMID 30898977, 2019). "To confirm these results, we selected three key genes involved in leukemia (interferon-regulatory factor 1 [IRF1], Caspase 8, and specificity protein 1 [SP1]) to confirm the gene expression of those factors was regulated by USP39." (PMID 30898977, 2019). "For instance, the deubiquitinating activity of USP9X regulates proper targeting and association of Survivin and Aurora B proteins to the centromeres, USP39 regulates the mRNA splicing of Aurora B, while USP14 was reported to regulate the stability of Aurora B in leukemia cells." (PMID 34445214, 2021).
melanoma (4 papers, 2019 to 2025). A malignant, usually aggressive tumor composed of atypical, neoplastic melanocytes. "In melanoma, USP39 is involved in melanoma progression by regulating cell cycle and apoptosis through the ERK1/2 signaling pathway." (PMID 40990019, 2025). "Immunohistochemical staining of clinical samples revealed that USP39 expression was markedly elevated in melanoma tissues compared to benign nevus tissues." (PMID 40672756, 2025). "In addition, the study also found that USP39 expression was elevated in poorly differentiated melanoma tissues, indicating a correlation between USP39 and the degree of tumor differentiation." (PMID 40672756, 2025). "Indeed, knockdown of USP39 induces cell cycle arrest and apoptosis in melanoma." (PMID 30898977, 2019). "The role of USP39 in indirectly affecting tumor progression by regulating key proteins of the MAPK pathway provides a new means and direction for the treatment of poorly differentiated refractory melanoma in the clinic, and targeted inhibitors of USP39 are worthy of further investigation." (PMID 40672756, 2025).
non-small cell lung carcinoma (4 papers, 2020 to 2025). A group of at least three distinct histological types of lung cancer, including non-small cell squamous cell carcinoma, adenocarcinoma, and large cell carcinoma. "miR-381 was downregulated in non-small-cell lung cancer tissues and cell lines, while USP39 was upregulated." (PMID 36046375, 2022). "Stronger staining of USP39 was observed in the non-small cell lung cancer (NSCLC) tissues, and mainly located in the nucleus." (PMID 33255748, 2020).
lentivirus infection (3 papers, 2015 to 2021). Virus diseases caused by the Lentivirus genus. "To further confirm the influence of USP39 on cell apoptosis, we used Annexin V-APC/7-AAD double staining on SMMC-7721 cells following lentivirus infection." (PMID 25889525, 2015).